FOXM1 (forkhead box M1)
Diseases named in the same sentence as FOXM1 in open-access papers (continued):
Sharing a sentence is not in itself a finding about the gene and the disease.
cancer (continued). "The present special Research Topic of Frontiers in Oncology is devoted to unveiling this new information, focusing on the role and regulation of FoxA1, FoxO3a, and FoxM1 in cancer initiation, progression, and drug resistance." (PMID 25401090, 2014). "On the other hand, suppression of FOXM1 delayed liver tumor growth in mice and inhibited the metastatic potential of human cancer cells in vitro." (PMID 25093142, 2014). "Previous studies have shown that the expression of FOXM1 was increased in different types of cancer." (PMID 24885308, 2014). "Previously, we showed that proteasome inhibitors suppress FOXM1 and induce apoptosis in human cancer cell lines of different origin." (PMID 25093142, 2014). "Mitochondrial oxidants are produced in excess in cancer cells due to oncogenic transformation and metabolic reorganization, and signals through FOXM1 and other redox-responsive factors to support a hyper-proliferative state." (PMID 25462069, 2014). "Re-expression of Foxm1 restored cellular proliferation in the SPDEF-positive cancer cells and rescued progression of SPDEF-positive tumors in mouse prostates." (PMID 25254494, 2014). "We proposed that the combination of FOXM1 suppression and induction of ROS by specific drugs would specifically kill human cancer cells." (PMID 25093142, 2014). "In his perspective article, Teh summarizes the existing information on the role of FoxM1 in cancer initiation, progression, and drug resistance, and explores its usefulness as a biomarker for cancer screening, prognosis, and for monitoring drug treatment." (PMID 25401090, 2014). "FoxM1 inhibitor, thiostrepton, induces apoptosis in cancer cell lines and enhances sensitivity to cisplatin in these cells." (PMID 25426548, 2014). "FOXM1 has a vital role in embryonic development, adult tissue homeostasis, cancer initiation and progression." (PMID 25287128, 2014). "Overall NPM interacts with FOXM1 and their interaction is critical for expression and cellular localization of FOXM1 in cancer cells." (PMID 25093142, 2014). "The forkhead transcription factor FOXM1 coordinates expression of cell cycle-related genes and plays a pivotal role in tumorigenesis and cancer progression." (PMID 25213081, 2014). "FOXM1 has also been shown to increase the resistance of cancer cells to apoptosis, and FOXM1 knockdown re-sensitizes tumor cells to programmed cell death." (PMID 24810962, 2014). "For example, gene expression profiles in carcinomas, including prostate, breast, lung, ovary, colon, pancreas, stomach, bladder, ovarian, liver, and kidney, revealed that FOXM1 is overexpressed in all carcinomas." (PMID 24824601, 2014). "Another transcription factor we found to be deregulated in multiple cancers is FOXM1, an oncogenic protein known to control proliferation, DNA damage repair, angiogenesis, and AOS response." (PMID 24342878, 2013). "Investigators found that transcriptional upregulation of FOXM1 expression accelerated the growth of hypoxic cancer cells by decreasing nuclear expression levels of p21 and increasing expression of cyclin B1 and cyclin D1." (PMID 24325450, 2013). "Obviously, further studies will be required to elucidate the precise mechanism of action of these compounds, and this will hopefully help to develop more selective and specific FoxM1 inhibitors for cancer treatment." (PMID 23467617, 2013). "One of the current limitations of targeting FoxM1 in cancer is its “druggability,” being a transcription factor." (PMID 23467617, 2013). "Overexpression of FOXM1 has been reported in many types of cancer and is correlated with poor prognosis." (PMID 23347430, 2013).
cancer (continued). "Thiostrepton, a thiazole antibiotic, has been already identified as having anticancer activity, and a number of studies have demonstrated its cytotoxic effect through selective inhibition of FoxM1 on a wide variety of cancer cell lines." (PMID 23857410, 2013). "In order to trigger cell cycle related events, it is possible that both GAPDH and FoxM1 translocate from the cytoplasm to the nucleus in cancer cells." (PMID 23620736, 2013). "Thiostrepton, a natural compound, has been shown to exert anti-proliferative effects against human cancer cells, mainly through inhibition of FoxM1 activity." (PMID 23857410, 2013). "FoxM1 knockdown sensitized cancer cells to apoptotic cell death induced by proteasome inhibitors such as MG-132, bortezomib and thiostrepton." (PMID 24148180, 2013). "As overexpression of FoxM1 has been reported in more than 20 types of human cancer and is involved in multiple landmarks of cancer, the inhibition of FoxM1 activity is emerging as an attractive target for cancer therapy." (PMID 23857410, 2013). "In cancer cells, which are usually subjected to enhanced mitogenic signals, elevated FOXM1 levels were found to promote the G1/S transition and to suppress senescence." (PMID 23386997, 2013). "The transcription factor FOXM1 is a master regulator for cell cycle progression and is overexpressed in a number of human cancers including GBM." (PMID 23404835, 2013). "Deregulated expression of FOXM1 results in centrosome amplification, mitotic catastrophe and other cytogenetic aberrations typically seen in cancer cells." (PMID 24130802, 2013). "Evidence suggests that FOXM1 is overexpressed in a variety of human cancers including breast, gastric, and lung cancers as well as glioma." (PMID 23365673, 2013). "FOXM1 enhances cancer stem cell self-renewal through direct binding to β-catenin inducing nuclear localization and transcriptional activity." (PMID 23404835, 2013). "Here, we review and discuss the molecular mechanisms through which FoxM1 executes these new roles, and the implications for the potential use of FoxM1 as a therapeutic target in cancer." (PMID 23467617, 2013). "In this work, FoxM1 was also identified as a critical substrate of CDK4/6 kinases that mediates senescence suppression in cancer cells through ROS regulation and the activation of genes required for the G1/S transcription." (PMID 23467617, 2013). "The inhibition of FOXM1 by genetic or pharmaceutical approach significantly impairs tumor growth of this cancer in vitro and in vivo, suggesting that targeting FOXM1 is an appealing and potential approach for anticancer therapeutics." (PMID 23819460, 2013). "The transcription factor FOXM1 has recently gained attention as a master regulator of mitotic progression of cancer cells in various organs." (PMID 23404835, 2013). "Accumulating evidences have shown that the upregulation of FOXM1 is often involved in the development of various human cancers." (PMID 23819460, 2013). "Our finding that growth and survival of DLBCL and BL in vitro is reduced using agents known to target FOXM1 extends a growing body of evidence for a role of this forkhead protein as a promising target of cancer therapy." (PMID 24130802, 2013). "During the last years, significant progress has been made in targeting FoxM1 in cancer [for a recent review see]." (PMID 23467617, 2013). "Thiostrepton, a naturally occurring small molecule, has been shown to selectively inhibit FoxM1 expression in cancer cells." (PMID 23857410, 2013). "Here, we summarize those findings on FoxM1 function in DNA damage and senescence processes, and its impact on therapeutic strategies against cancer." (PMID 23467617, 2013). "Accumulated evidence suggests that FOXM1 is a proto-oncogene with elevated expression in a number of human cancers such as liver, ovarian, breast, prostate, colon, and brain tumors including GBM." (PMID 23404835, 2013).
cancer (continued). "FOXM1 upregulation was also shown to promote cancer initiation and maintenance by inducing genomic instability." (PMID 23386997, 2013). "Significant progress has been made in the past years on FoxM1 function in DNA damage and senescence pathways, as well as in the possibilities of targeting FoxM1 in cancer." (PMID 23467617, 2013). "For instance, EPS8 has also been shown to upregulate FOXM1, an important factor in the development and progression of certain cancers which is known to directly bind with Sp1." (PMID 24367505, 2013). "Human cancer cells after FOXM1 suppression were subjected to doxorubicin or γ-irradiation treatment." (PMID 22393369, 2012). "Matrigel invasion assay showed that down-regulation of FoxM1 significantly suppressed the invasiveness of both cancer cells." (PMID 23006512, 2012). "On the other aspect, emerging evidences have found that the aberrant upregulation of FOXM1 transcription factor is involved in the pathogenesis of various human cancers." (PMID 23285101, 2012). "Since FOXM1 is widely expressed in human cancers, our data further support the fact that it is a valid target for combinatorial anticancer therapy." (PMID 22393369, 2012). "We and others have recently found that the upregulation of FOXM1 enhances cell proliferation, migration/invasion and particularly its expression is involved in cancer progression." (PMID 23285101, 2012). "We demonstrate that stable or transient knockdown of FOXM1 using RNAi increases the sensitivity of different human cancer cells to DNA-damaging agents including doxorubicin treatment and γ-irradiation." (PMID 22393369, 2012). "Its aberrant upregulation in almost all different cancer types suggests a fundamental role for FOXM1 in tumorigenesis." (PMID 23087907, 2012). "In the quest to understand the oncogenic mechanism of FOXM1, we have recently shown that FOXM1 induces cancer initiation by promoting adult human epithelial stem/progenitor cell renewal and by antagonising differentiation." (PMID 22461910, 2012). "Depletion of FOXM1 in mouse models of cancer markedly impedes tumor progression, indicating FOXM1 is an important factor in tumor progression." (PMID 22761781, 2012). "Our findings indicate that FOXM1 downregulation by stable or transient knockdown using RNAi or by treatment with proteasome inhibitors that target FOXM1 strongly sensitized human cancer cells of different origin to DNA-damage-induced apoptosis." (PMID 22393369, 2012). "Because STAT3 and FoxM1 are overexpressed in similar cancer types and coordinate similar cellular mechanisms, we investigated the relationship between FoxM1 and STAT3." (PMID 23110199, 2012). "Elevated expression of FoxM1 has been extensively reported in several solid tumor types and specifically has been closely related to cancer chemotherapeutics resistance." (PMID 23110199, 2012). "FOXM1 has emerged recently as an important cell cycle regulator that sits at the interface between oxidative stress, aging, and cancer." (PMID 22761781, 2012). "This led to the first evidence in normal primary human oral epithelial cells that FOXM1 induces a methylation landscape resembling a cancer epigenome found in HNSCC tumour tissues." (PMID 22461910, 2012). "The effect of FOXM1 was further confirmed by examining the expressions of known markers in cell migration/invasion, MMP-9 and uPAR, which are in line with the metastatic role of FOXM1 reported in other human cancers." (PMID 21858223, 2011). "Our data suggests that anti-FoxM1 siRNA can be functional when administered into tumors in an in vivo system, and that anti-FoxM1 siRNA holds potential as part of a therapy for cancer treatment." (PMID 22203467, 2011). "Both transcriptionally active splice variants of FOXM1; FOXM1B and FOXM1C are shown to be elevated in numerous human cancers." (PMID 21858223, 2011). "FOXM1 is also considered to be an oncogenic transcription factor, as its expression in cancer cells is found to be abnormally high." (PMID 22203467, 2011).
cancer (continued). "Forkhead Box M1 (Foxm1) is a transcription factor essential for organ morphogenesis and development of various cancers." (PMID 21779394, 2011). "In addiiton, in vitro studies have shown that the suppression of FOXM1 by siRNA sensitizes cancer cells to cell death upon stimulation with conventional chemotherapeutic drugs." (PMID 22203467, 2011). "Foxm1 signaling has been shown to be a critical mediator of both G1-S and G2-M transitions of the cell cycle, and to be upregulated in various human cancers." (PMID 21779394, 2011). "More importantly, the increased expression of FOXM1 has remarkable correlation with the progressive stages of numerous human cancers." (PMID 21858223, 2011). "We and other groups have previously reported that FOXM1 is frequently deregulated in a variety of human cancers." (PMID 21858223, 2011). "We recently showed that FOXM1 expression precedes malignancy in a number of solid human cancer types including oral, oesophagus, lung, breast, kidney, bladder and uterus indicating its pivotal role in cancer initiation." (PMID 20187950, 2010). "Here, we found that thiazole antibiotic-induced apoptosis in cancer cells of different origin was correlated with the downregulation of FoxM1." (PMID 19440351, 2009). "Thiopeptide-induced apoptosis correlated with the suppression of FoxM1 expression, while overexpression of FoxM1 partially protected cancer cells from the thiazole antibiotic-mediated cell death." (PMID 19440351, 2009). "Forkhead box M1 (FoxM1) oncogenic transcription factor represents an attractive therapeutic target in the fight against cancer, because it is overexpressed in a majority of human tumors." (PMID 19440351, 2009). "In our previous studies we demonstrated that thiazole antibiotics Siomycin A and thiostrepton induce apoptosis in human cancer cells and inhibit FoxM1 expression." (PMID 19672316, 2009). "PS-341 (bortezomib) is a newly developed proteasome inhibitor which induced apoptosis in cancer cells by inhibiting the activity of the Forkhead BoxM1 (FoxM1) transcription factor." (PMID 20339519, 2009). "Previously, we established that thiazole antibiotics Siomycin A and thiostrepton inhibit FoxM1 and induce apoptosis in human cancer cells." (PMID 19672316, 2009). "We also found direct correlation between the suppression of FoxM1 expression and induction of apoptosis by the thiopeptides in different human cancer cell lines." (PMID 19440351, 2009). "The degree of apoptosis induced by the thiopeptides correlates with the suppression of FoxM1, while overexpression of wild type FoxM1 partially protected cancer cells from thiopeptide-induced apoptosis." (PMID 19440351, 2009). "To evaluate the anticancer potential of the thiazole antibiotics we analyzed their effects on human cancer cell lines of different origin that had elevated expression level of FoxM1." (PMID 19440351, 2009). "Previously, we reported that thiazole antibiotics Siomycin A and thiostrepton inhibit FoxM1 and induce apoptosis in human cancer cells." (PMID 19440351, 2009). "Elevated FOXM1 levels have been found in numerous human tumors, suggesting that FOXM1 is required for cellular proliferation in human cancer cells." (PMID 19036130, 2008). "The transcription factor forkhead box M1 (FOXM1) has been shown to be up-regulated in a variety of carcinoma cell lines and its expression is suppressed in terminally differentiated cells." (PMID 18714348, 2008). "Similarly, the expression of FOXM1 and its targets correlates with cancer aneuploidy in time (AADEPT score), while other pro-proliferative transcription factors do not show this association (e.g., MYC)." (PMID 39930267, 2025).
cancer (continued). "Moreover, FoxM1 can upregulate the expression of cancer stemness genes, such as BMI1, NANOG, and c-MYC, in HCC cells." (PMID 40050970, 2025). "Notably, SCLC is a notorious cancer type that shows high metastasis and relapses with acquired CR, and our study provided the involvement of FOXM1 in the growth, metastasis, modulation of CR and immune response." (PMID 40630538, 2025). "According to the COSMIC catalogue for somatic cancer mutations, there is no focal point for FOXM1 mutations, which are not only rare but also evenly distributed across its protein sequence." (PMID 39858603, 2025). "DFOG downregulated the expression of OCSC markers and FOXM1, inhibiting cancer cell self-renewal." (PMID 40612352, 2025). "Additionally, Ning and colleagues have shown that DFOG effectively curtails the enhanced self-renewal abilities of cancer stem cells induced by abnormally elevated FOXM1 expression in OC cells." (PMID 40612352, 2025). "Moreover, differential gene expression analysis (DGEA) provided additional evidence of FOXM1 upregulation in cancer cells." (PMID 39858603, 2025). "So, FOXM1 overexpression in adults usually indicates cancer." (PMID 40003882, 2025). "Other targets of phosphorylation of CDK4 and CDK6 may also be of therapeutic interest in cancer, including transcription factors FOXM1, SMAD3 and NFAT4." (PMID 40699853, 2025). "If these limitations are overcome in the future, FOXM1 could become the ideal focus not only for biomarker development but also for pan-anti-cancer therapy." (PMID 39858603, 2025). "This suggests that cancer cells may use similar tuning of the FOXM1 expression program to resist the effects of RS‐inducing drugs without fully halting growth." (PMID 40009518, 2025). "For each human cancer, we chose the histologically more appropriate normal tissue available on GTEx (see Section 2), in order to investigate whether the FOXM1 transcript was altered in tumoral condition, relative to the most likely tissue of origin." (PMID 39858603, 2025). "We will then highlight the role of FOXM1 as a consistent overexpressor in cancer across the vast catalogue of tumor molecular samples available in the TCGA database, by comparing cancer signals with the largest transcriptional database for healthy human tissues, GTEx." (PMID 39858603, 2025). "FOXM1 is, however, scarcely mutated in cancer and does not always strongly appear as a pan-cancer predictor for survival." (PMID 39858603, 2025). "FOXM1 is also crucial for embryonic development and progression of malignant tumors." (PMID 40501685, 2025). "While we have no final explanation for this finding, it can be stated that normal thyroid is already a proliferating tissue, which may mask the pro-proliferative effect of FOXM1 in cancer." (PMID 39858603, 2025). "Furthermore, our investigation revealed that UBE2S, HIF‐1α, and FOXM1 exhibited significant upregulation in both esophageal intraepithelial neoplasia and cancer, with statistically significant variations observed." (PMID 41427004, 2025). "FOXM1 is highly expressed and a marker of poor prognosis in several cancers, including MPNST." (PMID 40002695, 2025). "Unlike canonical oncogenes, like BRAF or KRAS, FOXM1 is not commonly mutated nor amplified in cancer, warranting its exclusion from common “cancer gene lists” such as the Sanger Institute’s COSMIC Cancer Gene Census." (PMID 39858603, 2025). "However, overexpression of FOXM1 reversed this effect, enhancing the self-renewal capacity of OCSCs and promoting cancer cell stemness, leading to more severe disease." (PMID 40612352, 2025). "A large number of studies have shown that FOXM1 can promote the progression and metastasis of various cancers, as well as induce chemotherapy resistance, and has become a target for the treatment of various cancers." (PMID 39944135, 2025).